THOP1 (thimet oligopeptidase 1)
Diseases named in the same sentence as THOP1 in open-access papers (continued):
Sharing a sentence is not in itself a finding about the gene and the disease.
depression (1 paper, 2019). "Overall, the results presented here link THOP1 to brain disorders such as depression, attention and memory retention deficits, in addition to immune-stimulated neurodegeneration and infection induced inflammation." (PMID 31431000, 2019). "A role of THOP1 in the regulation of specific mRNA levels, depression-like behaviors, and deficit of attention and memory retention were first suggested herein." (PMID 31431000, 2019). "THOP1-/- mice presented a mild (p = 0.05) depression-like behavior in both FST and TST." (PMID 31431000, 2019). "In the second day of FST experiments, a mild depression-like behavior was observed for THOP1-/- mice, which exhibited slightly greater latency time to the first immobility episode as well as greater immobility periods during the 5 min of the FST experiments than WT control group." (PMID 31431000, 2019). "Therefore, THOP1 knockout mice reported here for the first time can be a new tool to investigate new drugs for neurodegenerative and inflammatory diseases as well as psychiatric disorders such as depression and deficit of attention." (PMID 31431000, 2019).
diabetic retinopathy (1 paper, 2020). "Human THOP1 was identified as having a role in early diabetic retinopathy, and genome-wide association studies identified THOP1 among the novel genetic features of cholesterol and lipoprotein metabolism." (PMID 32847123, 2020).
familial Alzheimer disease (1 paper, 2009). A degenerative disease of the brain that causes gradual loss of memory, judgment, and the ability to function socially. "Two proteins associated with human familial Alzheimer disease were constitutively expressed at all ages, thimet oligopeptidase 1 and valosin-containing protein." (PMID 19936306, 2009).
heart failure (1 paper, 2023). Inability of the heart to pump blood at an adequate rate to meet tissue metabolic requirements. "Interestingly, the mRNA expression level of THOP1 were downregulated in cardiac tissues from heart failure patients, which could be related to impaired cardiac energy metabolism in heart failure individuals." (PMID 38104081, 2023).
multiple sclerosis (1 paper, 2019). A progressive autoimmune disorder affecting the central nervous system resulting in demyelination. "In an experimental model of multiple sclerosis THOP1-/- mice present worse clinical behavior scores compared to WT mice, corroborating its possible involvement in neurodegenerative diseases." (PMID 31431000, 2019).
sarcoma (1 paper, 2022). A usually aggressive malignant neoplasm of the soft tissue or bone. "Considering that the expression of THOP1 has been repeatedly found upregulated in cancer cells compared to normal cells, including sarcomas, the prodrugs have potentially increased tolerability, tumor specificity and efficacy compared to conventional doxo." (PMID 35453612, 2022). "Since the clinical applicability of this route of administration was questionable and information on THOP1-related sensitivity was lacking, we further investigated intravenous administration of both CBR-049 and CBR-050 (another CoBioRes lead molecule) in 10 THOP1-expressing sarcoma xenograft models." (PMID 35453612, 2022).
schizophrenia (1 paper, 2019). A major psychotic disorder characterized by abnormalities in the perception or expression of reality. "ACE1 mRNA expression was seen to increase in ST and HC of THOP1-/- mice, and the ACE1 gene insertion/deletion polymorphisms has been shown to play a role in susceptibility to schizophrenia and also in its depressive symptom severity in a Han Chinese population." (PMID 31431000, 2019).
steatosis (1 paper, 2023). Increased lipid within the cytoplasm of cells. "The logistic regression model, -34.19 + 0.85 * QDPR*QDPR + 0.75 * CANT1*TYMP - 0.46 * THOP1*ALDH1A, achieved an AUC of 0.93 (95% CI: 0.63-0.99), with a sensitivity of 93% and specificity of 80% for detecting steatosis in individuals with PWS." (PMID 38034016, 2023).
Thrombocytopenia (1 paper, 2019). A reduction in the number of circulating thrombocytes. "Thrombocytopenia was also observed in THOP1-/- compared to WT mice, which could contribute to prolonged bleeding of these animals empirically observed following small surgical procedures (i.e., small tail/ear cuts for genotyping)." (PMID 31431000, 2019).
tumor (14 papers, 2007 to 2025). "Bioinformatics analysis suggested that miR-1307-5p promotes cancer progression by suppressing key tumor suppressor genes such as THOP1, EHF, RNF4, GET4, and RNF114." (PMID 40699851, 2025). "Bioinformatics analysis revealed that miR-1307-5p likely contributes to cancer progression by downregulating tumor-suppressive genes, such as THOP1, EHF, RNF4, GET4, and RNF114." (PMID 40699851, 2025). "The hydrolysis of Bradykinin by THOP1 induces the accumulation of intracellular calcium ions (Ca2+), leading to Ca2+ homeostasis which brings about tumour initiation, angiogenesis, progression and metastasis." (PMID 36142544, 2022). "While its activating enzymes are also expressed to a certain extent in normal tissues, tumor specificity is obtained considering that extracellular THOP1 is almost exclusively observed in cancer cells." (PMID 35453612, 2022). "Considering that the human tumor stroma is replaced by murine stroma throughout tumor growth in mice, part of the THOP1 expression that is produced by the tumor stroma is expected to be of murine origin." (PMID 35453612, 2022). "In a last step, we aimed to identify THOP1 as biomarker of sensitivity to the prodrugs by correlating tumor growth delay compared to control with the THOP1 expression level of each xenograft as determined by ELISA and IHC." (PMID 35453612, 2022). "There is a paucity of data on Thop1 expression and function in the placenta, however in the brain, a therapeutic potential as an anti-tumour agent has recently been reported." (PMID 26260700, 2015). "Although being considered to play a role in the neuroendocrine system, THOP1 has become a recent focus in tumor research." (PMID 25180910, 2014). "Accumulated evidence suggested that THOP1 was predominately expressed in the cytosol, endoplasmic reticulum, mitochondria and nucleus of different normal human tissues and tumor cells." (PMID 25180910, 2014). "According to our earlier defined criteria, high THOP1 expression was found in 49 (40.8%) of the 120 tumor specimens and low THOP1 expression was found in 71 (59.2%) of the 120 tumor specimens." (PMID 25180910, 2014). "Meanwhile, a trend towards more pronounced tumor growth delay could be observed for models with intermediate to strong THOP1 immunostaining." (PMID 35453612, 2022). "However, few studies have detected the expression of THOP1 protein in tumor tissues and its relationship to tumor prognosis." (PMID 25180910, 2014). "Our results implied that THOP1 protein may have an antitumor effect in carcinogenesis and tumor progression of NSCLC." (PMID 25180910, 2014). "Moreover, as an antagonist factor to BK, THOP1 could inhibit angiogenesis and tumor growth promoted by BK." (PMID 25180910, 2014). "Furthermore, THOP1 could inhibit tumor angiogenesis and tumor proliferation promoted by BK in melanoma cells." (PMID 25180910, 2014). "Although xenografts showed different THOP1 expression levels ranging from 23 to 299 ng/mg total protein as determined by ELISA, higher protein levels did not per se result in more pronounced tumor growth delay and vice versa." (PMID 35453612, 2022). "Therefore, we detected expression levels of THOP1 protein in patients with NSCLC by employing immunohistochemical method to investigate its correlation with clinicopathologic features, postoperative tumor relapse and prognosis." (PMID 25180910, 2014).
cancer (12 papers, 2014 to 2025). A tumor composed of atypical neoplastic, often pleomorphic cells that invade other tissues. "As such, further research on the degradation of neuropeptides by THOP1 will lead to interesting models for future investigations into the development of cancer." (PMID 36142544, 2022). "Future studies should address the relationship between increased THOP1 expression and enzymatic activity to all its related markers identified in this paper to ascertain its role in driving cancer progression." (PMID 34966482, 2021). "Exciting progress has been made in employing THOP1 for immunotherapy in cancers." (PMID 25180910, 2014). "Another study about cytotoxic T lymphocytes (CTLs) suggested THOP1 could strengthen the immune defense against intracellular pathogens and cancer by contributing to the C-terminal trimming of CTL epitopes." (PMID 25180910, 2014). "Therefore, decreased expression of THOP1 in NSCLC may be responsible for cancer development, malignancy and poor survival rate due to its reduction in anti-BK function." (PMID 25180910, 2014). "Previous studies showed GLRX3, GLRX5, WRNIP1, THOP1, and HSCB were all regulators of various cancer occurrence and progression." (PMID 34078439, 2021). "Thimet oligopeptidase (THOP1) is thought to be involved in neuropeptide metabolism, antigen presentation, neurodegeneration, and cancer." (PMID 31431000, 2019).
neurodegenerative disease (3 papers, 2019 to 2024). A disorder of the central nervous system characterized by gradual and progressive loss of neural tissue and neurologic function. "The IPA results also showed that most of the detected glycoproteins were associated with the activation of the gene THOP1, a gene that has been widely studied due to its expression changes during neurodegenerative diseases." (PMID 36359007, 2022). "Additionally, the analysis showed that most of the detected glycoproteins were associated with the activation of the gene THOP1, a gene that has been widely studied because its expression changes during neurodegenerative diseases." (PMID 36359007, 2022).
blood disorders (1 paper, 2019). "Complete blood count of THOP1-/- females before immunization showed increased percentage of granulocytes and monocytes and decreased percentage of lymphocytes compared to WT mice, suggesting intrinsic autoimmune or blood disorders of THOP1-/- animals." (PMID 31431000, 2019).
infection (1 paper, 2019). The state of being infected such as from the introduction of a foreign agent such as serum, vaccine, antigenic substance or organism. "Altogether, these results reveal a role of THOP1 on specific behaviors, immune-stimulated neurodegeneration, and infection-induced inflammation." (PMID 31431000, 2019).
psychiatric disorder (1 paper, 2019). A disorder characterized by behavioral and/or psychological abnormalities, often accompanied by physical symptoms. "These pharmacological responses suggest that disruption of THOP1 expression in mice induces a behavioral phenotype that resembles those seen in psychiatric disorders involving attention deficits." (PMID 31431000, 2019).
THOP1 also shares sentences with these, for which no sentence is quoted: atherosclerosis (3 papers); COVID-19 (3); influenza (3); Huntington disease (2); osteoarthritis (2); Parkinson (2); Stroke (2); acute myeloid leukemia (1); African trypanosomiasis (1); amyotrophic lateral sclerosis (1); aortic valve disease (1); Arthritis (1); autoimmune disease (1); brain disorder (1); clear cell sarcoma (1); coronary atherosclerosis (1); dementia (1); endometrial cancer (1); epilepsy (1); fibrosis (1); glioblastoma (1); hepatic (1); insulinoma (1); liver disease (1); liver steatosis (1); lymph node metastasis (1); maturity-onset diabetes (1); maturity-onset diabetes of young (1); metabolic disorder (1); primary immunodeficiency (1).
A further 4 diseases each share a sentence with THOP1 in 1 paper.